UCP2 (uncoupling protein 2)
Diseases named in the same sentence as UCP2 in open-access papers (continued):
Sharing a sentence is not in itself a finding about the gene and the disease.
cancer (continued). "Hence, it would be interesting to study the effect of organoselenium compounds on the redox status of the cancer cells in the obese microenvironment and understand the cross-talks mediated by UCP2." (PMID 33935708, 2021). "Therefore, we assume that enhanced expression of UCP2, which is found in most human cancer types, long lastingly facilitates mitochondrial ATP production by Ca2+-mediated stimulation of Krebs cycle dehydrogenases." (PMID 33614647, 2021). "In another study, UCP2 inhibited the proliferation of cancer cells by increasing ROS production." (PMID 33859525, 2021). "Interestingly, the activation of UCP2 also increases cancer proliferation potentially by increasing glycolysis and the expression of genes that promote mitobiogenesis." (PMID 33520711, 2020). "Mitochondria reduce ROS production to promote cancer cell survival through a complex regulatory feedback mechanism that may involve UCP2." (PMID 32190174, 2020). "Interestingly, UCP2 can remodel the metabolism toward the Warburg effect, by shifting cancer cells metabolism from mitochondrial oxidative phosphorylation (OXPHOS) to aerobic glycolysis." (PMID 32111081, 2020). "Furthermore, in the same cancer type the production of ROS by inhibition of the antioxidant mitochondrial uncoupling protein 2 (UCP2) stimulates the nuclear translocation of GAPDH which promotes autophagy." (PMID 31027346, 2019). "Also, UCP2-mediated alternation of normal metabolism into the specific cancer metabolism has been reported." (PMID 29351723, 2018). "Readers should bear in mind that, while inhibiting UCP2 could offer a therapeutic option in cancer cells, it could also be detrimental in some pathological conditions." (PMID 29587429, 2018). "Moreover, UCP2-mediated aspartate, oxaloacetate, and malate antiport with phosphate is expected to alter metabolism of cancer cells." (PMID 29351723, 2018). "The correlation between UCP2 and glutamine metabolism further links UCP2 to cancer development." (PMID 30011966, 2018). "Increased ROS production was observed also in UCP2 knockout mice, whereas UCP2 overexpression may contribute to a higher apoptotic threshold promoting cancer cell survival because it prevents oxidative injury." (PMID 30011966, 2018). "A notion that UCP2 is a stress-induced protein is valid also for cancer cells." (PMID 29351723, 2018). "Hence, UCP2 is overexpressed in many cancer cells and plays a key role both in tumorigenesis and in cancer progression." (PMID 29587429, 2018). "Speculations have been reported on both the cancer promoting and protecting role of UCPs, particularly UCP2." (PMID 29351723, 2018). "Notably, in this particular type of cancer also UCP2 expression was lower than in the adjacent normal tissue, possibly demonstrating that the mRNA expression of UCP2 and PRMT1 is dependent on the respective other protein." (PMID 29113301, 2017). "Furthermore, we observed that PRPF40A promoter remained unmethylated, while UCP2 promoter was sporadically methylated in few cancer samples." (PMID 28258342, 2017). "Since UCP2 overexpression is closely associated with enhanced cell proliferation and tumorigenesis, targeting UCP2 expression may be a winning therapeutic strategy to treat UCP2 overexpressed cancers." (PMID 29221144, 2017). "CRC cells are known to have increased levels of mitochondrial ROS, and UCP2 may function to help cancer cells avoid ROS-mediated apoptosis." (PMID 28423551, 2017). "The precise biologic functions of UCP2 in cancer regulation remain subject of debate." (PMID 29254145, 2017).
cancer (continued). "Our study reveals a major role of PRMT1 and UCP2 in cancer cell viability and proliferation as well as in patients’ overall survival probability, indicating that numerous different cancer types utilize upgraded mitochondrial Ca2+ uptake to meet their greatly enhanced energy demand." (PMID 29113301, 2017). "The consideration of UCP2 as a metabolite transporter has led to a more encompassing idea that UCP2 may contribute to cancer metabolism and malignant transformation." (PMID 29221144, 2017). "We and others have demonstrated that UCP2 is often highly expressed in human cancers." (PMID 29221144, 2017). "On the other hand, the present data suggest that cancer cells in the patient cohort with low levels of UCP2 and PRMT1 might be metabolically less active, yielding attenuated cancer cell proliferation and, thus, increased patient survival." (PMID 29113301, 2017). "By using UCP2/3, cancer cells may be able to counteract the impact of an essential PRMT1 activity to mitochondrial Ca2+ uptake and, thus, re-establish activity of mitochondrial Ca2+ uptake to achieve Ca2+-triggered activation of ATP production." (PMID 27642082, 2016). "Some data reveal that up-regulation of UCP2 may facilitate an increased chemoresistance as well as cancer adaptation to oxidative stress via mitochondrial suppression of reactive oxygen species (ROS)." (PMID 27551323, 2016). "GNP can induce apoptosis in many types of cancer cells by inhibiting UCP2 function." (PMID 26771380, 2016). "Indeed, UCP2 overexpression protects against ROS production and increases the apoptotic threshold for cancer cell survival, while UCP2 knockdown or pharmacological inhibition leads to an increase in mitochondrial ROS, as observed in UCP2 knockout mice." (PMID 27289382, 2016). "It has also been shown that expression of carnitine palmitoyltransferase 1c, a protein involved in mitochondrial fatty acid transport, or uncoupling protein 2 (UCP2) protects cancer cells from hypoxia and glycolysis inhibition by providing an alternative pathway for energy production." (PMID 25768019, 2015). "It was reported that increased expression of UCP-2 was found in many cancer cell lines, which might be related to the shifted energy metabolism status of cancer cells." (PMID 26107945, 2015). "UCP2 has been identified as a potential target for overcoming cancer chemoresistance." (PMID 26666173, 2015). "UCP2 was thus recognized as a negative regulator of mitochondrial ROS in many type of cancers." (PMID 26666173, 2015). "Additionally, proteins that are overexpressed in cancer cells are among the targets of down-regulated miRNAs in different treatment conditions, which includes Wnt3A, PPARα, UCP2, CSF1, and MED1." (PMID 24387052, 2014). "UCP2's occurrence in cancer, immunological and stem cells indicates that UCP2 is present in cells with highly proliferative potential, which have a glycolytic type of metabolism as a common feature, whereas UCP4 is strongly associated with non-proliferative highly differentiated neuronal cells." (PMID 24523901, 2014). "Furthermore, UCP2 overexpression strongly decreases gemcitabine-induced mitochondrial superoxide formation and protects cancer cells from apoptosis." (PMID 23966948, 2013). "In some cancers UCPs in particular UCP2 are highly upregulated and may contribute to the reprogramming of the cell metabolism that results in chemoresistance or even radioresistance." (PMID 23966948, 2013). "However, little is known regarding the precise role of UCP2 in cancer cells under hypoxic conditions." (PMID 22292025, 2012). "The impact of UCP2 on mitochondrial homeostasis is potentially so pervasive that it is difficult to identify a specific molecule or mechanism as the downstream effector of altered uncoupling in cancer cells." (PMID 21712825, 2011).
cancer (continued). "What makes UCP2 an appealing molecular tool of adaptation for cancer cells?" (PMID 21712825, 2011). "Nevertheless, new studies suggest UCP2 may interact with oncogenes and tumor suppressor genes, providing a potential new mechanism of how UCP2 contributes to cancer development." (PMID 21954358, 2011). "The near ubiquitous UCP2 becomes highly abundant in some cancers and may advance metabolic reprogramming, further disrupt tumour suppression, and promote chemoresistance." (PMID 21712825, 2011). "In summary, our studies demonstrate that i) the Warburg Effect is mediated by UCP2; ii) UCP2 is over-expressed in breast and many other cancers; iii) UCP2 promotes tumorigenic properties in vitro and in vivo and iv) genipin suppresses the tumor promoting function of UCP2." (PMID 21935467, 2011). "In addition, the widely expressed UCP, UCP2, has been shown to be upregulated in a number of aggressive human cancers." (PMID 21954358, 2011). "Later studies suggest that UCP2 is also involved in the pathogenesis of other cancers." (PMID 21954358, 2011). "Evidence is gathering that inhibition of UCP2 may thwart metabolic adaptation and antioxidant defence mechanisms in cancer cells." (PMID 21712825, 2011). "Whether increased UCP2 expression helps cancer cells to transform mitochondria into a sink of glycolytic ATP by invoking the reverse function of ANT2 and ATP synthase remains to be seen." (PMID 21712825, 2011). "Thus, UCP2-overexpressing cancer cells increasingly display the Warburg effect, and siRNA-mediated UCP2 knockdown leads to reversal of the glycolytic phenotype." (PMID 21712825, 2011). "From a therapeutic viewpoint, inhibition of glycolysis in UCP2 expressing tumours or specific inhibition of UCP2 are, respectively, attractive strategies to target the specific metabolic signature of cancer cells or enhance the effectiveness of ROS-inducing agents." (PMID 24281083, 2010). "Our results suggest that the contribution of UCP2 in cancer cells might be more complicated than described before." (PMID 20976134, 2010). "This function of UCP2 may be especially important in cancer cells since their mitochondria are metabolically abnormal." (PMID 20967268, 2010). "Regarding the second strategy, UCP2 could be a potential target of drugs designed to fight against therapy-resistant cancers." (PMID 24281083, 2010). "Thus, the chemical inhibition of UCP2 with genipin sensitizes multidrug-resistant cancer cells to cytotoxic agents." (PMID 20967268, 2010). "One mechanism by which aggressive cancers that over-express UCP2 might inhibit glycolytic ATP is the so-called Randle cycle." (PMID 19480693, 2009). "The goal of the current study was to test the hypothesis that ketone bodies can inhibit cell growth in aggressive cancers and that expression of uncoupling protein 2 is a contributing factor." (PMID 19480693, 2009). "It is reasonable to ask whether one can take advantage of the ability of UCP2 to disrupt regulation of ATP generation in cancer as a therapeutic method." (PMID 19480693, 2009). "Here, we aimed to determine whether UCP-2 and -3 expression was similarly up-regulated in human cancer." (PMID 11875702, 2002).
cancer (continued). "Finally, we examined whether STAT1 and UCP2 expression could have prognostic value for cancer patients." (PMID 41367865, 2025). "However, the specific contributions of UCP2 to cancer biology remain poorly defined." (PMID 38986826, 2024). "However, the current literature about the role of UCP2 in cancer is controversial." (PMID 38986826, 2024). "Consequently, UCP2 exhibits dual functionality in cancer, acting as a tumor suppressor in normal cells but functioning as an oncogene in established tumors, where it may confer resistance to chemotherapy and survival advantages by reducing oxidative stress." (PMID 39795950, 2024). "Comparing UCP2 levels after long-term exposure of K562 to CoCl2 and proliferation recording, results show a correlation in decreased UCP2 and decreased proliferation upon hypoxia-mimicking conditions, suggesting that these cancer cells depend on UCP2 under hypoxia." (PMID 38986826, 2024). "Thus, UCP2 represents a promising target for therapeutic interventions in cancer treatment." (PMID 38217303, 2024). "In addition to its possible role in controlling ROS generation and chemoresistance, it has been proposed that UCP2 could also be involved in the metabolic reprogramming of the cancer cell." (PMID 37175829, 2023). "Targeting UCP2 could be a potential strategy for cancer treatment." (PMID 37744277, 2023). "The activation of UCP-2 may play an important role in decreasing ROS production but has a detrimental effect on cancer because many studies have established that the overexpression of UCP-2 in cancer cells decreases ROS production in cancer cells and helps them to thrive." (PMID 36900198, 2023). "However, depending on the stage and type of cancer, UCP2 has a dual regulation mechanism." (PMID 36499405, 2022). "Therefore, UCP2 can be a potential biomarker for cancer resistance." (PMID 35628447, 2022). "Finally, we will explore whether targeting UCP2 could represent a therapeutic advantage in the fight against cancer and resistance to therapies." (PMID 36499405, 2022). "Moreover, overexpression of Rab32, a protein kinase A-anchoring protein fostering the ER-mitochondrial tethering, leads to a decline in the expression of UCP2, which points to an adaption strategy of cancer cells to escape mitochondrial Ca2+ overload-induced cell death." (PMID 33614647, 2021). "Based on these results, we assume that cancer cells successfully manage mitochondrial Ca2+ uptake to stimulate Ca2+-dependent mitochondrial metabolism while avoiding Ca2+-triggered cell death by fine-tuning ER-mitochondrial tethering and the expression of UCP2 in an inversed manner." (PMID 33614647, 2021). "Furthermore, ErbB2 induces the overexpression of the uncoupling protein 2 (UCP2) in cancer cells." (PMID 32655416, 2020). "Human UCP2 displays 59% sequence identity with hUCP1, and it is expressed in many tissues including the brain, lung, kidney, spleen, thymus, pancreas and heart, as well as in fast-proliferating cells using aerobic glycolysis, such as cancer, pluripotent stem and immune cells." (PMID 32842667, 2020). "The ubiquitous presence of UCP2 mRNA may be required for rapid protein production to adapt to changing metabolic conditions, for instance, facilitating rapid proliferation in activated immune and cancer cells." (PMID 31133866, 2019). "Hence, we thought to exploit these mechanistic insights to improve anti-cancer therapy and asked whether Genipin, an inhibitor of UCP2, enhances cellular sensitivity to cisplatin induced apoptosis." (PMID 31699970, 2019).
cancer (continued). "That is, we and several other groups have previously demonstrated that UCP2, which mRNA was found nearly ubiquitously, is present at protein level exclusively in highly proliferating cells, which have a glycolytic type of metabolism, such as cancer, stem and activated immune cells." (PMID 29988383, 2018). "Hence, UCP2 overexpression is thought to confer a growth advantage for cancer cells." (PMID 29221144, 2017). "In addition, highly expressed UCP2 could confer chemoresistance and inhibition of UCP2 expression sensitizes cancer cells to chemotherapy." (PMID 29221144, 2017). "In contrast to accelerated ROS production at complex III of the mitochondrial electron transport chain upon acute exposure of cells to hypoxic conditions, the HIF-1/PPARγ/UCP2 pathway defined here may represent a long-term mode of ROS regulation and maintenance in hypoxic carcinomas." (PMID 28042952, 2017). "The inhibition of UCP2 allows ROS accumulation and genomic instability, while the negative regulation of mitochondrial ROS production through UCP2 over-expression usually occurs during cancer development, chemo-resistance, and tumor metastasis to defend cancer cells from apoptosis." (PMID 26771380, 2016). "Based on the presented and previous results, demonstrating the expression of UCP2 in embryonic cells, cancer cells, (activated) lymphocytes and macrophages, we suggest that the presence of UCP2 may be characteristic for cells with high proliferative and anabolic potential." (PMID 24523901, 2014). "In cancer cells, UCP2 may play an integral role in the adaptive response to chemotherapeutics." (PMID 22292025, 2012). "Selective inhibition of UCP2 may cancel many benefits of metabolic reprogramming in cancer cells." (PMID 21712825, 2011). "Collectively, our studies suggest that i) UCP2 over-expression in tumors is a common phenomenon; ii) UCP2 over-expression promotes tumor development and iii) UCP2 over-expression can serve as a promising therapeutic target for treatment of breast and many other cancers." (PMID 21935467, 2011). "The effect is consistent with an "inefficient" Randle cycle due to over-expression of uncoupling protein 2, seen only in the cancer lines, and is plausible in light of current models of a transformed cell's adaptive microscopic development and progression toward the cancer phenotype." (PMID 19480693, 2009). "Upregulation by lipid-mobilizing factor of uncoupling proteins-1, -2 and -3 in brown adipose tissue, and of uncoupling protein-2 in skeletal muscle and liver, suggests that these uncoupling proteins may serve to utilize excess lipid mobilized during fat catabolism in cancer cachexia." (PMID 11870545, 2002). "UCP-2 mRNA levels in muscle seems unaffected by cancer either with or without weight loss." (PMID 11875702, 2002). "In this context, the overexpression of Uncoupling protein 2 (UCP2) and the ensuing reduction in mitochondrial ROS levels have been observed in cancer cells." (PMID 40298834, 2025). "Gene set enrichment analysis (GSEA) indicated that UCP2 expression positively correlates with EMT and immune modulation pathways, suggesting its dual role in promoting cancer cell invasion and regulating the tumor immune microenvironment." (PMID 41403699, 2025). "To this end, we performed real-time cell metabolism analysis, Western blotting and proliferation assays on several murine and human cancer cell lines, including CRISPR-Cas-9 generated UCP2 KO cell lines." (PMID 38986826, 2024).